IL6 (interleukin 6)
Diseases named in the same sentence as IL6 in open-access papers (continued):
Sharing a sentence is not in itself a finding about the gene and the disease.
infection (continued). "Excessive production of cytokines (interleukin 6 (IL-6), tumor necrosis factor α (TNFα)) in response to infection can lead to systemic inflammation and CNS manifestations." (PMID 39439614, 2024). "The content of PCT, TNF‐α, and IL‐6 was markedly elevated in infection stage group than the control group (p < .05)." (PMID 38577990, 2024). "MAP infection induces the upregulation of IL-6 released by macrophages when measured after 24 hr and 48 hr of infection (2.8 ± 0.72 pg/mL and 2.5 ± 0.67 pg/mL, respectively) compared to untreated controls (0.25 ± 0.06 pg/mL)." (PMID 39170608, 2024). "IL-6 is a major mediator of the acute-phase response, which is a systemic reaction to infection, inflammation, or tissue injury." (PMID 39273060, 2024). "This implies that during the early stages of infection and inflammation, IL-6 and IL-17 generate a protective response." (PMID 38279220, 2024). "On day 7 after infection, the lungs of IL-6−/− + rIL-6 mice (1.44 × 106 CFU/g) had significantly higher fungal burden than Wild-type (4.09 × 105 CFU/g; P < 0.01) and IL-6−/− (3.92 × 105 CFU/g; P < 0.01) mice, respectively." (PMID 39334365, 2024). "A statistically significant reduction in IL-1β levels in culture supernatants was seen 24 hours post-infection with AN_CH_37, as well as other pro-inflammatory cytokines, namely IL-6 and TNF-α." (PMID 38590438, 2024). "For example, infection with Middle East Respiratory Syndrome Coronavirus (MERS-CoV) increases the levels of IFN-γ, TNF-α, and IL-17, while infection with SARS-CoV-2 leads to increased levels of IL-6, IL-12, and IFN-γ." (PMID 38355623, 2024). "Co-staining demonstrated the presence of Ly6G and IL-6 double-positive cells in lung tissue sections from MHV68-infected K-RasLA1 mice 7-days post-infection." (PMID 39338937, 2024). "At three weeks post-infection, we found that IL-6 and G-CSF cytokines were upregulated in the plasma." (PMID 40295722, 2024). "For IL-6, infection induced an increase in this cytokine in all groups compared to the healthy control (p < 0.0368)." (PMID 39598539, 2024). "Activation of peripheral blood mononuclear cells after interactions with Cn increases the levels of IL-6 and augments their resistance to infection." (PMID 39334365, 2024). "The variability in the literature concerning IFN-γ underscores the significance of our study, which assessed IFN-γ at multiple infection stages and examined the dynamic release patterns of IL-4, IL-1β, and IL-6." (PMID 39408907, 2024). "IL-6 is produced in response to infections and tissue injuries, and contributes to host defense by stimulating acute phase responses." (PMID 39081865, 2024). "IL-6 is a pleotropic cytokine typically released in the context of infection and tissue damage induced by toll-like receptors (TLRs) and damage-associated molecular proteins (DAMPs), often in association with IL-1β and TNFα." (PMID 39595087, 2024). "Previous studies on mice support our findings of the significant increases in IL-6 protein concentrations following ST infection." (PMID 38465263, 2024). "We investigated the expression of IL-1β and IL-6 mRNAs in the early phase of infection at four and eight hpi with different C. jejuni strains." (PMID 38907359, 2024). "IL-6, which is mainly secreted by neutrophils, plays an important role in innate immune defense against infections." (PMID 38251210, 2024). "Functionally, NKB cells have been described as expressing several cytokines, including IL-1b, IL-6, IL-12, and IL-15, upon stimulation/infection, in addition to their signature IL-18 secretion." (PMID 38739675, 2024). "Infection during pregnancy activates the maternal immune system to enhance the production of proinflammatory cytokines, such as IL-6, IL-17, and TNF-α." (PMID 38593153, 2024). "IL-6 was usually indicative of the initiation of an acute-phase response and were upregulated following primary infection with E. maxima." (PMID 38492183, 2024).
infection (continued). "HuN2021 infection was accompanied by the upregulation of proinflammatory cytokines, such as IL-6, IL-1β, IL-8, TNF-α, and CCL8, as well as the immunomodulatory cytokines IL-10 and IFN-γ, at the mRNA and protein levels." (PMID 39506759, 2024). "Established markers such as C-reactive protein (CRP), procalcitonin, and interleukin-6 (IL-6) indicate infection presence and severity, aiding clinical decision-making." (PMID 38465031, 2024). "The mRNA expression of IFN-α, IL-1α and IL-6 showed divergent results depending on the virus used and the time of infection." (PMID 39772252, 2024). "Infection with SARS-CoV-2 showed a decreased expression of IL-6 measured at 3 and 24 hpi and of IFNα at 3 hpi and IL-1α at 24 hpi compared to uninfected control cells." (PMID 39772252, 2024). "The inflammatory response triggered by postoperative infection, leading to increased production of IL-6 and VEGF, is considered one of the mechanisms contributing to anastomotic leakage." (PMID 38715036, 2024). "Similar to what was seen in human macrophages, the secretion of IL-6 was highly induced in the capsule mutant and lower in the L. longbeachae WT at 24 hours post-infection." (PMID 39259722, 2024). "Astrocytes can activate innate antiviral pathways upon infection with HSV-1–such as IL-6, TNF-α, and type I IFN production via the TLR3-dependent pathway in HSV-2 infection." (PMID 39339840, 2024). "Spinal cords of wild-type mice contained significantly higher levels of IFN-β and IL-6 at day 5 post-infection (p ≤ 0.05) and IFN-γ, IL-1β, CCL3, CCL5, and CXCL9 at 5 and 9 days post-infection (p ≤ 0.05)." (PMID 39339840, 2024). "On the contrary, the transcription of il-6 (pro-inflammatory gene) and il-10 (anti-inflammatory gene) was significantly up-regulated in response to infection with any of the viruses." (PMID 38921776, 2024). "In detail, levels of pro-inflammatory factors, including interleukin (IL)-6, IL-8, and IL-17A, peaked on the first day of infection and gradually declined in the subsequent days." (PMID 38765687, 2024). "IBV DMV/1639 infection led to notable upregulation of IL-1β and IL-6 mRNA expressions at various early time points, diverging from IBV Conn A5968-infected TOCs and non-infected controls." (PMID 39472003, 2024). "Conversely, IL-5, IL-6, and IL-12 (P40) experienced a notable decrease on day 4 post-infection, suggesting a distinct regulatory role of c-FLIP in macrophages compared in vivo." (PMID 39038037, 2024). "Specifically, maternal exposure to IL-6, either through direct administration or as a result of infection, led to epigenetic remodeling in the intestinal stem cells of adult offspring." (PMID 39508347, 2024). "IL-6 is a pro-inflammatory factor produced during tissue injury and infection, playing a vital role in immune and inflammatory processes, as well as cellular proliferation and differentiation." (PMID 38473757, 2024). "In CNS EV-71 infection, cytokines such as IL-6, IL-8, and CXCL10/IP-10 have been observed in the CSF, which correlates with an increase in the recruitment of monocytes and neutrophils in this fluid." (PMID 38248274, 2024). "Our previous study reported that the pro-inflammatory factors IL-1β and IL-6 secreted by macrophages were markedly reduced following the coaggregated S. gordonii and Fnp infection." (PMID 38761182, 2024). "Conversely, CRP is produced by the liver in response to interleukin-6 (IL-6), which is generated during infection and inflammation." (PMID 39669267, 2024). "We observed significant differences (p < 0.01) between the groups for CRP and IL-6 levels that were higher in moderate/severe disease than in mild infection." (PMID 39518479, 2024). "According to clinical experiences, CRP, PCT, and IL-6 showed rapid increase in the early stage of infection." (PMID 39039507, 2024).
infection (continued). "Interleukin-6 is a multifunctional cytokine that regulates cell growth, differentiation, and function, mediating the response to injury or infection, immune diseases, and cancer." (PMID 39251966, 2024). "XBB.1.5 infection resulted in an average 19.64- and 25.72-fold increase in IL-6 levels at 3 and 5 dpi, respectively." (PMID 39417078, 2024). "The expression of IL-6, an essential factor produced by the innate immune system during the initial response to infection, was compared between 2 groups on days 1 and 7 after treatment." (PMID 39495969, 2024). "Of interest, these patients have elevated neutrophil-to-lymphocyte ratios, indicating inflammation, and importantly, elevated high-sensitivity C-reactive protein and interleukin-6 levels in the initial phases of the infection." (PMID 39355453, 2024). "Pro-inflammatory cytokines such as TNF-α, IL-1β, IL-6, and IL-2 play several key roles in the brain, as follows: (i) They are crucial in initiating and regulating inflammation in response to infection, injury, or disease." (PMID 39337280, 2024). "They showed lower concentrations of the MyD88-dependent cytokines TNF-α, IL-6 and G-CSF – all involved in the early stages of infection – thus suggesting the inability of RR in mounting an immediate inflammatory response." (PMID 39723217, 2024). "Knockdown of DARS2, but not related mt-aaRS in BEAS-2B cells significantly attenuated the release of the innate immune cytokines IL-1β, IL-6, and TNFα in response to infection with PA103." (PMID 39039092, 2024). "In contrast, only few pg/ml IL-6 can be detected in healthy individuals, but these amounts can rise by several orders of magnitude during inflammation and infection." (PMID 39835136, 2024). "After the piglets were challenged with PEDV, the IL-6 and IL-1β levels were significantly decreased in both the challenge and cohabitation infection groups with oral administration of the mutant strain S1/△Alr HLJ-27." (PMID 38430229, 2024). "Epithelial cells are early responders to infection and induce downstream effectors such as IL-6, IL-8, TNF-α, IFN-γ, and nitric oxide (14, –, 16)." (PMID 38407132, 2024). "The presence of IL-6 in umbilical blood is normative during uneventful term deliveries, with elevated values indicative of potential infection." (PMID 39062232, 2024). "WT and HuR KO RAW264.7 cells were infected with 1 MOI HAZV and at 9 h post infection, the expression of Il6, Ifnb, Tnf, Cxcl10, Il10, Il12p40, Ccl2 and Tgfb relative to non-infected control cells and the copy number of S segment inside cells were measured." (PMID 39348382, 2024). "In chickens, the inflammatory factors HMGB1 and IL-6 are widely expressed in the lungs after Pm infection." (PMID 39850582, 2024). "Activation of ERK and NF-κB by S. typhi WT infection was impaired in Klra17-/- PEMφs; consequently, IL6 production was diminished in Klra17-/- PEMφs." (PMID 38720899, 2024). "We also found that IL-6 levels at 72 hours after infection were significantly lower in the plasma of mice treated with CETPi, as compared with those with control." (PMID 38646937, 2024). "Infection with AdV2 showed a reduction in expression for IL-6 and INFα at 24 hpi compared to the uninfected control cells." (PMID 39772252, 2024). "IL-6 is a critical cytokine produced in response to infection or tissue damage and required to mount immune response sequentially." (PMID 38257829, 2024). "We propose that analogous to the sequence of increases in IMs after surgical trauma, the acute immune response in infection is initiated by IL-6." (PMID 38709460, 2024). "We found that the AUC of IL-6 combined with PCT for predicting postoperative infection was 0.89 (95% CI: 0.84–0.93)." (PMID 38504206, 2024). "Unlike TNF-alpha, which is usually undetectable on day 10 post-intravenous infection in our mouse model, IL-6 levels remain measurable in the later phase of the disease." (PMID 39204252, 2024).
infection (continued). "C/EBPβ is essential in the synthesis of acute phase proteins (APPs) in hepatocytes in response to IL6 released from leukocytes during infection or injury." (PMID 39261648, 2024). "Mice treated exclusively with mAb 8E6 exhibited increased levels of IL-6 in the lungs at the onset of infection (4 h, p = 0.041; 24 h, p = 0.038)." (PMID 39460288, 2024). "WT, Rig-I/Mda5 KO, IPS1 KO, and Tbk1/Ikk-i KO MEFs were infected with 1 MOI HAZV, and Ifnb, Il6 and Tnf expression was measured at 24 h after infection." (PMID 39348382, 2024). "While type-1 T-cells induce IL-6, IL-1β, TNF-α, and IL-12 production by monocytes/macrophages to fight the infection, type-2 T-cells are associated with a regulatory phenotype (IL-10 and TGF-β) and successful infection establishment." (PMID 39192975, 2024). "In instances of infection, hepcidin expression levels increase early, following IL-6 release by immune cells and Toll-like receptor (TLR) stimulation by Gram-negative bacteria-derived lipopolysaccharide (LPS)." (PMID 39691716, 2024). "IL-6 is a pro-inflammatory and pleiotropic cytokine with multiple functions, especially in the immune response to infections." (PMID 39495782, 2024). "During the different time points (24 h, 48 h, and 7 days post-infection), a variation was detected for IL-6, IL-1β, considering the three different concentrations." (PMID 38399810, 2024). "During infection, the hepatic synthesis of hepcidine is stimulated by several inflammatory cytokines, such as IL-6, IL-1, and TNFα." (PMID 38787184, 2024). "An important element to note about IL-6 that is directly related to critical ischemia is that an immediate expression of IL-6 is generated in response to environmental stressors such as infection or tissue injury." (PMID 38672153, 2024). "Our results showed an overall reduction in secretion of TNF, IL-6 and IL-12p40 after infection of RAW264.7 macrophage cells with Ms_Rv2231c." (PMID 38698289, 2024). "The severity of infection can be partially identified by the expression level of IL-6 according to earlier research." (PMID 38337668, 2024). "IL-6 is transiently produced during infection and tissue damage, stimulating acute-phase responses, hematopoiesis, and immune responses." (PMID 38786737, 2024). "In contrast, SeVeGFP infection resulted in a significant release of IL-6 and CXCL10, albeit at ten-fold lower levels as compared to stimulation with a pro-inflammatory cocktail." (PMID 39351233, 2024). "This aligns with the outcomes of the ROC curve analysis, which showed that IL-6 had the highest AUC value among all factors, including existing infection markers such as CRP and PCT." (PMID 39654974, 2024). "Among the six cyto/chemokines detectable by the array, we observed a significant rise in MCP1, TNFα, and interleukin 6 (IL6) in JEV-infected N9 cells at 6 h post-infection (HPI) and 24 HPI." (PMID 38869276, 2024). "Activated neutrophils release pro-inflammatory cytokines, such as TNF-α, IL-1β, and IL-6, exacerbating inflammation instead of providing protection as observed in infection and tissue injury scenarios." (PMID 38794163, 2024). "Contrary to these findings, anin vitro study reported a significant decrease in IL-6 in mice at day 9 post-infection with a model containing the MS1987 protein (Fraser-pittet al., 2023)." (PMID 39981106, 2024). "CRP is a protein induced by IL-6 in the liver, and it is evidenced by sensitive biomarkers of inflammation, infection, and tissue damage in response to exertion." (PMID 39595661, 2024). "In the secondary infection group, the mRNA expression level of IL-6 in VB was significantly higher than that in B and V at 4 dpi (P < 0.001), and that in BV was significantly higher than that in B and V at 6 dpi (P < 0.001)." (PMID 40303164, 2024). "IL-6, a pleiotropic cytokine, plays a pivotal role in various processes encompassing pathogen infection and immune system activation." (PMID 38971783, 2024).
infection (continued). "A study conducted on primary human brain endothelial cells revealed that infection with recombinant, wt NiV-Malaysia induces high levels of inflammatory cytokines such as IL-6, TNF-α, IL-8, eotaxin, MCP-1, MIP-1β and IP-10." (PMID 39466030, 2024). "The results of this study suggest that IL-6 is a valuable prognostic marker that increases significantly even in the early stages of infection." (PMID 39654974, 2024). "The more rapid response to DD infection for IL-6 was only found for chronic (M4) lesions and focal flare-ups (M4.1)." (PMID 39595313, 2024). "Our studies have shown that during infection with both L. europaeus genotypes, the level of IL-6 increases most in the spleen." (PMID 39273479, 2024). "In conclusion, from a single infection, the streptococci and CNS quarter showed varied immune responses, including trendily higher IL-6 and IL-4." (PMID 39195804, 2024). "By binding to VP1 of EV-A71, lactoferrin plays a role in the viral attachment stage while being able to induce the expression of interferon α (IFN-α) and down-regulate the expression of interleukin-6 (IL-6) induced by EV-A71 infection." (PMID 37001813, 2024). "The mRNA expression of IL-6 in colon tissue was significantly increased due to infection and the mRNA of IL-1b also tended to increase." (PMID 39081865, 2024). "Subsequently, we assessed the diagnostic capabilities of CRS, fever, PCT, IL-6, and CRP in the early diagnosis of infection in febrile patients after CTI using the ROC curve and the Youden’s index." (PMID 38956649, 2024). "These symptoms are often associated with severe disease as they can be triggered by increased inflammatory factors (e.g., interleukin-6) during infection." (PMID 39247070, 2024). "IL-6 plays a role in infection control through various mechanisms, and its inhibition can impair HSV control, potentially leading to viral reactivation." (PMID 39502960, 2024). "Inhibition of both SIRT1 and SIRT3 increased production of pro-inflammatory cytokine IL-6 significantly at 2 hr and 20 hr post-infection." (PMID 39693143, 2024). "Secondary infections, accounting for 38.2% of cases, exhibited earlier elevations of IL-6 and IL-10 than primary infections, suggesting that pre-existing immune memory primes faster cytokine release." (PMID 39457019, 2024). "IL-6 is produced by various cell types, including macrophages, fibroblasts, and endothelial cells, in response to a wide range of stimuli, including infection, tissue damage, and inflammation." (PMID 38914713, 2024). "TNFα and IL-6 were significantly raised in right vagotomized mice at days 3 and 8 post-infection, respectively, and left vagotomized mice showed an increase in IFNγ at day 8 post-infection." (PMID 38626267, 2024). "The proportion of M1 cells in mice tissues increased in the early stage of infection, suggesting that macrophages mainly differentiated into M1 macrophages and released pro-inflammatory factors (IL-1, IL-6, ROS, etc.)to kill bacteria." (PMID 39323765, 2024). "The increased mouse serum IL-6 and IL-1β production was in a similar line with the increased IL-6 or IL-1β cytokine generation in EX-527 or 3TYP treated peritoneal macrophages under the infection scenario." (PMID 39693143, 2024). "Multiplex ELISA assay on culture supernatants confirmed that infection-stimulated secretion of IL6 and IL8, as well as of several other cytokines and chemokines, was reduced in cells expressing ISG15 compared with ISG15-KO HeLa cells." (PMID 39345209, 2024). "Hepcidin production is also induced by IL-6 during infection, which leads to the transient inhibition of subsequent FPN-mediated iron transport, resulting in decreased serum iron levels." (PMID 38883134, 2024). "IL-6 and IL-8 are involved in the initiation and propagation of inflammatory responses, with IL-6 acting more broadly in inducing fever and acute-phase responses, while IL-8 specifically recruits neutrophils to sites of infection or injury." (PMID 38920561, 2024).